PAX8 (paired box 8)
Diseases named in the same sentence as PAX8 in open-access papers (continued):
Sharing a sentence is not in itself a finding about the gene and the disease.
tumor (continued). "Four of the tumours were negative for CK, CK7, CK8, PAX8, AE1/AE3 and HMB45." (PMID 26201545, 2015). "While tumour weights and volumes were not significantly higher in LAM1:PIK3CAE545K mice, there was a decrease in expression of thyroid differentiation markers TTF-1, thyroglobulin, PAX8 and B-catenin, suggesting that introduction of PIK3CAE545K led to dedifferentiation in vivo." (PMID 35193694, 2022). "Immunohistochemically, the tumor cells showed strong cytoplasmic expression for CK7, S-100, vimentin, EMA, nuclear expression for SOX10, focal membranous for CA9, and were negative for thyroglobulin, actin, calponin, PAX8, CD10, CK20, CDX2, CD117, DOG-1 and SMA." (PMID 29041930, 2017).
cancer (164 papers, 2005 to 2026). A tumor composed of atypical neoplastic, often pleomorphic cells that invade other tissues. "It was found that higher PAX8 gene expression was associated with a lower cancer cell differentiation and lower survival rate." (PMID 34540435, 2021). "In cancer, mutations in PAX8 have multiple downstream consequences affecting cell proliferation, adhesion, and angiogenesis." (PMID 34925233, 2021). "From these results, the combination of 3D cluster status and ICC with CK7 and PAX8 permitted the ability to construct a diagnostic decision tree to help identify the primary cancer which metastasized into the peritoneal cavity." (PMID 30024911, 2018). "In this article, we review the functions of the PAX8 gene, how its mutations lead to the development of certain epithelial carcinomas, how it can be used as a diagnostic or a prognostic marker, and its potential as a therapeutic target for these cancers." (PMID 34540435, 2021). "Based on a single color tracing of PAX8+ cells and analysis of cancer-associated mutations, recent studies have suggested that normal endometrial epithelial cells might expand clonally." (PMID 32998907, 2020). "PAX8 is a cell-lineage-specific transcription factor that has been mainly characterized in the thyroid gland for its role in thyrocyte differentiation, and it has been revealed as a potential diagnostic marker for several cancer sites including TC." (PMID 32294918, 2020). "However, a better knowledge of genes transcriptionally regulated by PAX8 is desirable to clarify its role in endocrine syndromes and cancer susceptibility." (PMID 26030152, 2015). "Moreover, gene expression profiling in normal versus malignant thyroid tissues demonstrated a downregulation of DIO1 and DIO2, which could be linked to Pax8 loss during cancer progression." (PMID 22531031, 2012). "The expressions of CK5/6, Pax-8, P40, and P63 at the peripheral and mesenchymal junctions of the cancer foci were focally positive." (PMID 41847703, 2026). "Single-cell transcriptomic data, accessed via the TISCH portal on 28 March 2025, showed that PAX8 is highly expressed in multiple cell populations, including cancer cells." (PMID 40506992, 2025). "The presence of cancer cells in ascites was first evaluated by PAX8 ICC, as it is the most common and cost-effective approach for HGSOC pathological diagnostics." (PMID 40051502, 2025). "Both PAX2 and PAX8 can modulate similar cellular pathways, such as proliferation, differentiation, survival, metastasis and metabolism in a cancer context." (PMID 40506992, 2025). "The silencing of PAX8 in cancer cells induces cell-cycle arrest and leads to reduction in the expression of E2F1 and its target genes." (PMID 40506992, 2025). "Immunohistochemistry results were as follows: cancer cells Pax-8 (+), P16 (+), CK7 (+), and CDX-2 (-)." (PMID 41127008, 2025). "For instance, Cytokeratin 7-expressing cells serve as models for studying the early transition from normal epithelium to cancer cells, while PAX8-expressing cells contribute to understanding cancers originating from fallopian tube epithelium." (PMID 40034272, 2025).
cancer (continued). "Pax8 belongs to a class of spectrum survival genes that are required for both the normal development of certain tissues and the proliferation of cancer cells." (PMID 39062676, 2024). "Regarding immunohistochemical staining, most sRCC stain positive for AE1/AE3, vimentin, CK OSCAR, PAX-8, and epithelial membrane antigen owing to the epithelial origin of the cancer." (PMID 39564030, 2024). "The successful analysis of 15,223 cancers provides a comprehensive overview on PAX8 expression in cancer." (PMID 39105782, 2024). "The HLTCs showed diffuse positivity for CK7 (which was even stronger than in the conventional carcinoma component) and PAX8." (PMID 39408649, 2024). "The expression of DCAF8 and PAX8 in tumors illustrates patterns of significant downregulation (p = 0.0262) and upregulation (p = 0.00174) across cancer stages 1 and 3, respectively." (PMID 36831395, 2023). "PAX8 expression was significantly lower in gastric‐ and iSMILE‐type cancers than in intestinal‐ and usual‐type cancers (p < 0.001)." (PMID 35861118, 2023). "PAX8 is used as a marker to distinguish carcinoma of gynecologic origin from carcinomas originating from other organs and mesothelioma." (PMID 37231035, 2023). "We detail the role of PAX8 in each of these organ systems, describe its role during development and in the adult if known, and highlight its pro-tumorigenic role in cancers that emerge from PAX8 expressing organs." (PMID 35806410, 2022). "The comparison of PAX8 expression and its role in development and cancerous tissues highlights the connections between embryonic development and cancer formation." (PMID 35806410, 2022). "In this manuscript, we aim to explore the reactivation of this specific fallopian tube embryonic marker in the context of other developmental processes that are reactivated in cancer, and in the context of other PAX8 roles." (PMID 35806410, 2022). "We found a small cluster that expressed the marker gene for hematopoietic cells (PTPRC) and that for cancer cells (PAX8)." (PMID 35892844, 2022). "In preoperative molecular FNAC diagnostics, the aggressiveness of cancers with the most frequently occurring mutations (BRAF, RAS, RET/PTC, TERT, PAX8/PPAR-γ, RET proto-oncogene) is correlated with the extent of the planned surgical treatment." (PMID 35884820, 2022). "Immunophenotypically, the carcinoma was consistent with thyrocyte differentiation with expression of monoclonal PAX8, TTF1, and thyroglobulin (the last predominantly in extracellular colloid)." (PMID 34997561, 2022). "Although present with ADSC CM, inhibiting PAX8 also restrained the proliferation of cancer cells, and the PAX8 overexpression had the similar proliferation‐promoting effect of ADSCs CM." (PMID 33830648, 2021). "We also shed some light on the role of PAX8 in the development of various cancers, such as thyroid, renal, ovarian, endometrial, cervical, and ocular, as well as thymic epithelial carcinomas." (PMID 34540435, 2021). "Surgery appears to be recommended when a molecular alteration is detected, particularly BRAF or PAX8/PPARγ which are highly specific for cancer." (PMID 32638211, 2021). "PAX8 is mostly known as a developmental TF required for the establishment of follicular thyroid cells in mice and humans; however, its role in cancer is still under investigation." (PMID 33903593, 2021). "As expected, CAFs expressed PDGFRβ and FSP1, and cancer cells E‐cadherin and PAX8, whereas both cell types were positive for vimentin and N‐cadherin." (PMID 32115889, 2020). "Conversely, FOXE1+/− cancers show a weaker staining for both PAX8 and TG, with the positive cells surrounding and partially filling the follicle-like structures." (PMID 33375029, 2020).
cancer (continued). "A statistically significant difference was noted for the PAX-8 staining and cancer type with P value < 0.001." (PMID 32847623, 2020). "Differentiation of BRAF FOXE1+/+ and BRAF FOXE1+/− cancers was analyzed by IHC for two representative differentiated thyroid markers, the transcription factor PAX8, and the precursor of thyroid hormones thyroglobulin (TG)." (PMID 33375029, 2020). "Based on site of cancer, all endometrium carcinoma showed positive expression of PAX-8 with P value < 0.001." (PMID 32847623, 2020). "Accordingly, immunofluorescent staining of paxillin and F-actin demonstrated abnormally enhanced focal adhesions in PAX8-depleted cancer cells." (PMID 31050342, 2019). "Here, we identified an ovarian lineage-specific PAX8 regulon using modified cancer outlier profile analysis, in which PAX8-FGF18 axis was responsible for promoting cell migration in an autocrine fashion." (PMID 31050342, 2019). "In this study, we uncovered a lineage-specific PAX8 regulon in EOC by conducting modified cancer outlier profile analysis (COPA) on RNA sequencing (RNAseq) data of a large cell line panel." (PMID 31050342, 2019). "Future studies should also aim at characterizing the protein complexes engaged by PAX8 in different contexts (RCC vs. Ovarian and normal vs. cancer) in order to provide a rational for novel drugs that can inhibit the function of PAX8 in cancer cells." (PMID 31431624, 2019). "The restricted expression pattern of PAX8 was exploited for lineage tracing experiments to determine the cell of origin of cancer." (PMID 31431624, 2019). "By implementing deliberate computational and epistatic analyses, a nine-gene PAX8 regulon as cancer outlier has been described and revealed to exhibit lineage-restricted expression pattern in both neoplastic ovarian tissues and normal fallopian tubes." (PMID 31050342, 2019). "PAX8, a product of the pair-box gene family, plays a complex role in the developmental of various disease including cancers." (PMID 29997452, 2018). "Pax8 is aberrantly expressed in several cancer types including papillary thyroid carcinoma, cervical tumors, and glioblastoma." (PMID 30021604, 2018). "A large number of studies have shown that PAX8 strikingly expressed in several types of tumors, exerts its biological functions and ultimately affects the development of cancer." (PMID 29997452, 2018). "In HGSC, PAX8 provides growth advantages by enhancing the proliferative, migratory, and survival capabilities of cancer cells from the fallopian tube and ovary." (PMID 30096791, 2018). "The PAX proteins are promising because PAX8 is ubiquitously expressed in serous tumors and PAX2 loss is an early molecular event shared in the progression from benign to malignant carcinoma." (PMID 30096791, 2018). "PAX8 is important for embryogenesis of the thyroid, Müllerian system, and upper urinary/renal tract, and expression of PAX8 has been described in carcinomas from each of these sites." (PMID 28634564, 2017). "The present study revealed that PAX8 was expressed in carcinoma cells of 34 cases and sarcomatoid cells of 27 cases." (PMID 28449664, 2017). "PAX8 was expressed in carcinoma cells in 34 of 42 cases (34/42) and sarcomatoid cells in 11 of 42 cases (27/42) (P = 0.141)." (PMID 28449664, 2017). "Overall, PAX8 belongs to a class of lineage-survival genes that are required for both normal development of specific tissues and for cancer cell proliferation/survival." (PMID 27259239, 2016). "Other gene fusions involving transcription factors include NUT (or NUTM1), POU5F1, MAML2, NFIB, PLAG1, TFE3, NOTCH, and PAX8 fusions, imparting spatially and/or stochastically dysregulated expression in multiple different cancer types." (PMID 26684754, 2015). "It is not surprising that PAX8 knockdown results in significant loss in A549 cell viability; as such a role was demonstrated for PAX transcription factors including PAX8 in the promotion of cancer cell growth." (PMID 24628993, 2014).
cancer (continued). "When combining with Calretinin, PAX8 is a sensitive and specific marker defining the cancers of ovarian or tubal origin." (PMID 23958394, 2013). "Among the 22 meatstatic cancers into the pelvis, the staining results were as follows: PAX8+/Calretinin- (n = 1), PAX8-/Calretinin + (n = 0), and PAX8-/Calretinin- (n = 21)." (PMID 23958394, 2013). "In this study, we evaluated the utility of PAX8 antibody in recognition of cancer cells of ovarian origin for the patients prior to receiving neoadjuvant therapy." (PMID 23958394, 2013). "Moreover, the embedding of malignant cell aggregates indicated that cell invasion of CK7 + cells (expressed in cancer cells and mesothelial cells) and cell proliferation of both PAX8- and PAX8 + cells was enhanced in OHGs compared to collagen gels." (PMID 41022685, 2025). "Additionally, a strong nuclear positivity for PAX8 is maintained in carcinomas from the thyroid, kidney, and Müllerian tract." (PMID 40506992, 2025). "A liver biopsy confirmed PAX-8 positive carcinoma, consistent with metastatic renal cell carcinoma." (PMID 40370715, 2025). "Furthermore, strong nuclear positivity for PAX8 is maintained in carcinomas originating from the thyroid, kidney, and Müllerian tract." (PMID 40506992, 2025). "Rare cancer biomarkers such as Pax8, Pax2, napsinA, carbonic anhydrase IX, claudin-4, Cdx-2, and others have been identified and studied thoroughly to help provide a better diagnosis of rare cancer." (PMID 38256274, 2024). "Taken together, the information regarding the role of PAX8 in HGSCs fits its definition as a master regulator transcription factor of HGSCs, regulating about 30,000 genes and governing many hallmarks of cancer such as evading apoptosis, angiogenesis, and migration." (PMID 35806410, 2022). "In addition, another study found that the knockdown of PAX8 significantly reduces cancer cell proliferation, migration, and invasion." (PMID 34917619, 2021). "We will also discuss the significance of PAX8 immunostaining in detecting these cancers." (PMID 34540435, 2021). "Because PAX8 is important for the development of the thyroid, it has been speculated that the fusion of PPARγ and PAX8 can lead to cancer by activation of aberrant gene transcription." (PMID 34359735, 2021). "Our data confirms that PAX8/PPARγ rearrangements are cancer specific." (PMID 32638211, 2021). "Nowadays, molecular testing in DTCs suggests a high risk for recurrence of cancer associated with BRAFV600E, RET/PTC 1/3, ALK and NTRK fusions, while the intermediate risk may be related to BRAFK601E, H/K/N RAS and PAX8/PPARγ." (PMID 33922518, 2021). "In addition, PAX8 is a promising therapeutic target as its expression is restricted in normal tissues, compared to its role in cancer." (PMID 34925233, 2021). "Molecular testing in DTTs documents a high risk for recurrence of cancer associated with BRAFV600E, RET/PTC 1/3, ALK and NTRK fusions, while the intermediate risk may be related to BRAFK601E, H/K/N RAS and PAX8/PPARγ." (PMID 33922518, 2021). "In addition, FACS analysis confirmed that LDR-mediated PAX8 induction was interrupted by miR-330-5p mimics treatment in BCPAP cancer cells." (PMID 30760304, 2019). "Indeed, PAX8 belongs to a class of lineage-survival genes that are required for both normal development of specific tissues and for cancer cell proliferation/survival." (PMID 31832016, 2019). "Likewise, PAX8 knockdown also harbored LDR-mediated suppression of BRAF-induced cellular transformation in 850-5C cancer cells as observed by sphere forming and soft agar colony forming assays." (PMID 30760304, 2019).